PRAMEF20 (PRAME family member 20)
Synonyms: PRAMEF21; OTTHUMG00000007911; OTTHUMT00000008157
Tractability: No criterion of Open Targets' tractability assessment is met for any kind of drug.
Gene: Protein-coding gene on chromosome 1 (13,410,450 to 13,421,328, forward strand). Ensembl gene ENSG00000204478.
Gene Ontology:
Molecular function: ubiquitin-like ligase-substrate adaptor activity
Biological process: proteasome-mediated ubiquitin-dependent protein catabolic process; negative regulation of apoptotic process; negative regulation of cell differentiation; negative regulation of DNA-templated transcription; positive regulation of cell population proliferation
Cellular component: Cul2-RING ubiquitin ligase complex; cytoplasm
Genetic constraint (gnomAD): Loss-of-function variants: 27 observed, 33.79 expected, observed/expected ratio (o/e) 0.8, 90% interval 0.59 to 1.1. The upper end of that interval is the gene's LOEUF score, 1.1, which puts it in group 4 of 6, group 1 being the genes least tolerant of losing a copy. Missense variants: 604 observed, 600.32 expected, observed/expected ratio (o/e) 1.01, 90% interval 0.94 to 1.08. Synonymous variants: 256 observed, 242.22 expected, observed/expected ratio (o/e) 1.06, 90% interval 0.95 to 1.17.
Homologues: Orthologues: chimpanzee PRAMEF20 (97% identical), mouse Pramel13 (45% identical), rat Pramef20 (44% identical), mouse Pramel15 (44% identical), rat LOC120103107 (44% identical), rat Pramef8 (44% identical), mouse Pramel12 (44% identical), rat Pramef5 (44% identical), rat Pramef12 (43% identical), mouse Pramel16 (43% identical), rat Pramef20l1 (43% identical), mouse Pramel31 (43% identical), and 79 more. Paralogues in human: PRAMEF6 (82% identical), PRAMEF15 (82% identical), PRAMEF25 (82% identical), PRAMEF26 (82% identical), PRAMEF5 (82% identical), PRAMEF11 (81% identical), PRAMEF4 (81% identical), PRAMEF9 (81% identical), PRAMEF27 (81% identical), PRAMEF12 (63% identical), PRAMEF8 (62% identical), PRAMEF7 (62% identical), and 12 more.
Diseases named in the same sentence as PRAMEF20 in open-access papers:
PRAMEF20 is named in the same sentence as 1 disease in open-access papers, as found by Europe PMC text mining. Sharing a sentence is not in itself a finding about the gene and the disease. The quoted sentences say what the papers report.
cancer (1 paper, 2024). A tumor composed of atypical neoplastic, often pleomorphic cells that invade other tissues. "On the other hand, the T165P mutation in PRAMEF20 with the largest βi = +5.95 is predictive of cancer, controlling for all other mutations." (PMID 39172974, 2024).